APOA5 (apolipoprotein A5)
Diseases named in the same sentence as APOA5 in open-access papers (continued):
Sharing a sentence is not in itself a finding about the gene and the disease.
dyslipidemia (continued). "The aim of this study was to determine the interaction of dietary fat intake with the APOA2 (rs3813627 and rs5082), APOA5 (rs662799 and rs3135506) and LEPR (rs8179183 and rs1137101) polymorphisms and its relationship with obesity and dyslipidemia in young subjects." (PMID 26365669, 2015). "The objective of this study was to analyze the interaction of a high fat diet with the APOA2 (rs3813627 and rs5082), APOA5 (rs662799 and rs3135506) and LEPR (rs8179183 and rs1137101) polymorphisms and its relationship with obesity and dyslipidemia in young subjects." (PMID 26365669, 2015). "Such association of APOA5 towards dyslipidemia was accompanied by a 21% decrease of the CD4 T-cell count (p=0.024) and a 19% increase in CD8 T-cell count (p=0.002) in carriers of the rare allele in the APOA5 rs662799 polymorphism adjusted by age and gender." (PMID 25394062, 2014). "Indeed, our previous studies have shown that the APOA5 and APOA1-C3-A4 genetic polymorphism was associated with dyslipidemia in Taiwanese population." (PMID 23249574, 2012). "Secondly, adjustment for triglycerides (but not for other metabolic syndrome-related criteria) abolished the associations between APOA5 or APOA4 SNPs and the risk of metabolic syndrome." (PMID 18789138, 2008). "Additionally, rs117026536 in the LPL gene, rs651821 in the APOA5 gene, rs9926440 in the CETP gene, and rs429358 in the APOE gene were associated with dyslipidemia.The GWAS analysis of the male subjects revealed 13 significant SNPs in the discovery stage (P < 5 × 10− 8)." (PMID 36419087, 2022). "Speculatively, it is suggested that the APOA5 −1131T>C polymorphism do not produce categorical dyslipidemia but functions as modifier for serum HDL-C and TG levels according to SCG." (PMID 21860654, 2012). "Mainly present in genes of lipid metabolic pathways (APOA5, APOB, APOC3 and LPL), the higher frequency of risk alleles in Puerto Ricans has been associated previously in other populations with unfavorable lipid profile and insulin response, cardiovascular conditions and metabolic syndrome." (PMID 19682384, 2009). "Furthermore, the APOA5 -12,238C and APOA4 Ser347 alleles were associated with a lower risk of metabolic syndrome – possibly due to their negative linkage disequilibrium with the APOA5 Trp19 allele." (PMID 18789138, 2008). "Moreover, a genetic polymorphism study in the Chinese population also demonstrated a correlation between the metabolic control and ApoA5 gene in patients with NAFLD, but whether the serum ApoA5 level is associated with metabolic syndrome and NAFLD remains unknown." (PMID 35854768, 2022). "Next, we divided participants into four groups according to the quartiles of the ApoA5 concentration to explore the relationship of the serum ApoA5 level with NAFLD, metabolic profiles, and the prevalence rate of NAFLD and metabolic syndrome in detail." (PMID 35854768, 2022). "For instance, ZPR1 and BUD13 were well-documented for lipid level, HERPUD1 was found related to HDL-C in the Korean population, and the APOA5 and CETP also showed evidence of contributing to triglycerides, metabolic syndrome, and HDL-C." (PMID 35238325, 2022). "Similarly, variants in the 11223.3 chromosomal region involving APOA1, APOA4, APOA5, and APOC loci were reported to be strongly influencing the lipid levels and dyslipidemia in studies from northern and southern India." (PMID 38348409, 2023).
coronary artery disease (44 papers, 2010 to 2025). "A major breakthrough was made in a collaborative analysis of 101 studies, in which a causal association between triglyceride levels and coronary artery disease was found on the basis of the rs662799 polymorphism in the promoter of APOA5." (PMID 40004488, 2025). "The protein encoded by APOA5, apolipoprotein A5 (APOA5), plays an important role in regulating plasma TG levels and as a major risk factor for coronary artery disease." (PMID 39050255, 2024). "Subsequent studies revealed that loss-of-function mutations in human APOA5 are associated with high plasma TG levels and an increased risk of atherosclerotic coronary artery disease." (PMID 38880127, 2024). "Han Chinese populations from Southeast Asia harbor a pathogenic APOA5 missense variant (p.G185C) that has been linked to elevated plasma TG levels and an increased risk for coronary artery disease." (PMID 38880127, 2024). "APOA5: Rare variants in the Apolipoprotein A5 (APOA5) gene disrupt triglyceride metabolism and increase susceptibility to ischemic heart disease." (PMID 37965396, 2023). "Several studies have reported an association between APOA5 gene single nucleotide polymorphisms and coronary artery disease." (PMID 36071387, 2022). "On the other hand, the impact of MIF and APOA5 on HF are likely mediated by the risk of coronary artery disease, a leading cause of HF." (PMID 35964012, 2022). "The SNPs in KALRN (rs9289231), ATP10D (rs2351791), CUBN (rs2291521), and APOA5 (Rs662799) are all significantly associated with the risk of coronary artery disease (CAD)." (PMID 36071494, 2022). "BAG3 is significantly and negatively associated with systolic and diastolic blood pressure, whereas MIF and APOA5 are associated with coronary artery disease." (PMID 35964012, 2022). "Multivariable MR showed that association of BAG3, MIF and APOA5 with HF were mediated by the blood pressure and coronary artery disease." (PMID 35964012, 2022). "The APOA5 gene is most commonly altered at -1131 T > C, this polymorphism being closely associated with a number of diseases, such as hypertriglyceridemia and coronary heart disease." (PMID 33836655, 2021). "The gene ZPR1 is known to interact with the triglyceride-associated gene APOA5, which plays an important role in regulating plasma triglyceride levels, a major risk factor for coronary artery disease (CAD)." (PMID 33763119, 2021). "Later, Tang et al23 reported that c.553G>T in the APOA5 gene is associated with an increased risk of developing coronary artery disease and altered TG levels in a Chinese population." (PMID 31901151, 2020). "Among these SNPs, rs662799, which is located in the promotor region of the APOA5 gene, was associated with TG levels and coronary heart disease in a Japanese and a Chinese population." (PMID 31910446, 2020). "Logistic regression analysis adjusted for possibly confounding factors (sex, age, BMI, and smoking) showed a significant association between c.56C > G APOA5 variant and coronary artery disease." (PMID 32832146, 2020). "APOA5 gene on chromosome 11q23.3 is known to be associated with dyslipidemia, which is a component of MetS, and a risk of coronary heart disease." (PMID 31910446, 2020). "APOA5 (OMIM 606368) or apolipoprotein A5 is associated with plasma triglyceride levels, a major risk factor for coronary heart disease." (PMID 27152866, 2016). "Our results showed that APOA5 56C > G and -1131 T > C polymorphisms play a major role in elevated risk of developing coronary artery disease due to its association with increased plasma TG." (PMID 24684850, 2014). "APOA5 comprises 4 exons encoding 366 amino acids and is an important determinant of plasma triglyceride (TG) levels, a major risk factor for coronary artery disease." (PMID 23509746, 2013). "APOA5 gene variants were also reported to be associated with the lipid levels and the risk of coronary heart disease in T2D patients." (PMID 23922971, 2013).
coronary artery disease (continued). "Therefore, the present study was designed to examine the implication of the c.56C > G APOA5 variant as a coronary artery disease risk factor in the Moroccan population." (PMID 32832146, 2020). "Moreover, large scale population genetic studies indicated that loss of function mutations in APOC3 and APOA5 gene conferred decreased and increased risk of coronary artery disease (CAD), respectively." (PMID 31836003, 2019). "The APOA5 gene is located on chromosome 11q23 and encodes an apolipoprotein protein that has been implicated in regulating the plasma triglyceride levels, a major risk factor for coronary artery disease (CAD)." (PMID 27827461, 2016). "Thus, our data show markedly higher systolic and diastolic blood pressure in subjects with the APOA5 H2 and APOA5 H4 haplotypes, which may explain the higher risk of coronary heart disease associated with the 56G and -1131C alleles." (PMID 24684850, 2014). "A study of the South Korean men reported that, in patients with hyperglycemia or coronary artery disease, serum ApoA5 was positively correlated with TG, while in patients with normal TG, it was negatively correlated." (PMID 35854768, 2022). "SNPs in LPL and posttranscriptional regulators of LPL including ANGPTL4, APOA5, APOC3, and ANGPTL3 that modulate plasma TAGs have been persuasively linked to coronary artery disease (CAD)." (PMID 29563332, 2018). "Triglycerides (TGs) are proatherogenic lipoproteins involving the risk of coronary heart disease (CHD), while apolipoprotein A5 (APOA5) and apolipoprotein C3 (APOC3) are main lipoproteins composing TG-rich lipoproteins." (PMID 26387083, 2015). "However, some proteins such as BAG3, MIF and APOA5 show concordant associations between HF, the blood pressure (BAG3) and coronary artery disease (MIF and APOA5)." (PMID 35964012, 2022). "For example, loss-of-function mutations in apolipoprotein C3 (APOC3), which is an inhibitor of LPL, decrease the risk of coronary artery disease (CAD), while loss-of-function mutations in apolipoprotein A5 (APOA5), which is an activator of LPL, increases the risk of CAD." (PMID 27039080, 2016). "For rs651821 (APOA5), carriers of the T allele also had lower HDL cholesterol levels, but individuals with the C/C genotype (wild-type homozygotes) in the low-fat intake group showed a significantly reduced risk of coronary artery disease (interaction p-value = 0.0155)." (PMID 40077648, 2025). "Hyperlipidemia is a risk factor of arteriosclerosis, stroke, and other coronary heart disease, which has been shown to correlate with single nucleotide polymorphisms of genes essential for lipid metabolism, such as lipoprotein lipase (LPL) and apolipoprotein A5 (APOA5)." (PMID 29425239, 2018). "APOA5 can reduce triglyceride (TG) and increase HDL, representing a protective factor for coronary heart disease." (PMID 33836655, 2021). "For example, the genes including LPL, APOA5, LIPC and CETP reported in the previous and present studies were involved in lipid metabolism and coronary artery disease (CAD)." (PMID 24386095, 2013). "Currently, no approved drugs target APOA5 for the treatment of coronary artery disease, and previous epidemiological studies and fundamental experiments have also indicated its association with CAD." (PMID 40649979, 2025).
Obesity (39 papers, 2012 to 2025). Accumulation of substantial excess body fat. "Although some studies suggest that PCSK9 and APOA5 are positively associated with comorbid depression and obesity, reproducible associations with depressive symptoms are limited, given their strong metabolic effects." (PMID 41375608, 2025). "In particular, ApoA5 modulates the excessive accumulation of triglycerides in adipose tissue, which is the hallmark of obesity." (PMID 39280566, 2024). "A genome-wide methylation array analysis of patients with obesity and controls revealed a significant inverse association between the level of methylation within the APOA5 locus and obesity." (PMID 38927431, 2024). "The current study suggests the role of APOA5 genetic variants in determining the responses of MetS and obesity to dietary fiber related to plasma TG levels." (PMID 38581036, 2024). "In a study of 151 obese women undergoing weight loss dietary intervention, the genotype of the apolipoprotein A5 (APOA5) gene, which is associated with obesity and cardiovascular metabolic risk, influenced the effectiveness of the dietary intervention." (PMID 38192650, 2023). "APOA5 is one of the strongest regulators of plasma TG concentrations and has been linked to obesity." (PMID 30053818, 2018). "Evidence have established an association between the presence of APOA5 gene SNPs and the risk of obesity." (PMID 30053818, 2018). "The interaction of G Allele of ApoA5 c.56C>G polymorphism with LPL polymorphism to heighten the genetic susceptibility to obesity have also been reported." (PMID 24708648, 2014). "Next, the association between APOA5 variants and obesity-related traits in obese or overweight children were examined." (PMID 24903888, 2014). "Given that APOA1, APOC3, and APOA4 are genes associated with obesity and are grouped together in the same cluster as APOA5, it is possible that mutations in one gene within the cluster may be caused by genetic variations in another gene." (PMID 38867151, 2024). "Both APOA2 and APOA5 were linked to increased risk of obesity and metabolic syndrome." (PMID 31831817, 2019). "They found that C-allele of APOA5 SNPs was associated with higher HDL and the GC haplotype, which was composed of the G-allele of APOA1 SNPs and the C-allele of APOA5 SNPs, was significantly associated with obesity, with higher glycated hemoglobin, and fasting glucose." (PMID 30053818, 2018). "Interactions between APOA5 and other genes with obesity risk have also been studied." (PMID 30053818, 2018). "Individuals carrying the APOA5 56 G/G genotype with a high saturated fatty acid consumption ≥12 g/d (OR = 2.7, 95 % CI 1.3–5.6; P = 0.006) and/or total fat ≥83 g/d (OR = 2.4, 95 % CI 1.2–4.9; P = 0.018) were associated with an increased risk of obesity." (PMID 26365669, 2015). "Individuals carrying the APOA5 56 G/G genotype with a high saturated fatty acid consumption (OR = 2.7, p = 0.006) and/or total fat (OR = 2.4, p = 0.018), associated with an increased risk of obesity." (PMID 26365669, 2015). "Our available data supported the hypothesis that the TG-raising genetic variants in the APOA5 gene may also have high risks for obesity in Chinese children and adolescents." (PMID 24903888, 2014). "One speculated mechanism is that the effect of APOA5 gene variants on the risk of obesity might be attributed to this locus being in interaction with other obesity-risk genes, such as APOA1, APOC3 and APOA4 genes." (PMID 24903888, 2014). "In conclusion, we herein demonstrated the TG-raising genetic variants in the APOA5 gene may influence the susceptibility of the individual to obesity, which may also contribute to an increased risk of high non-HDL-C levels in Chinese obese children and adolescents." (PMID 24903888, 2014). "Our study aims to compare the relationship between the demographic characteristics and the biochemical parameters of the participants and biomarkers (BMP1, NRG4 and ApoA5) thought to be related to obesity." (PMID 39280566, 2024).
Obesity (continued). "The fact that the plasma level of ApoA5 is consistently low in obese individuals and that it is inversely correlated with BMI supports the relationship between ApoA5 levels and the pathophysiology of obesity." (PMID 39280566, 2024). "Based on these physiological functions, recent study results have identified the link between the APOA5 gene and metabolic disorders, including obesity and MetS." (PMID 38581036, 2024). "In Mexican populations aged 18 to 25 years, the risk of obesity (2.7 times, p = 0.006) and low HDL cholesterol (2.1 times, p = 0.018) was increased in those with the G allele of APOA5 rs3135506 and saturated fatty acid intake ≥ 12 g/day." (PMID 35468744, 2022). "It has also been suggested that MET reduces hepatic TG accumulation and improves obesity-related NAFLD by inhibiting hepatic apolipoprotein A5 (ApoA5) synthesis through the AMPK/LXRα signaling pathway." (PMID 36429065, 2022). "It was of note that the presence of both polymorphisms of APOA5 and ZPR1 in homozygosity showed a stronger relationship with moderate/severe NAFLD than the presence of other well-known factors, such as obesity or high glucose or TG concentrations." (PMID 33567543, 2021). "We found that LPL, APOA5, and CETP were associated with the metabolically unhealthy phenotypes in individuals with normal weight or obesity." (PMID 33500527, 2021). "In summary, our findings implicate apoA5 in metformin-mediated amelioration of obesity-induced NAFLD." (PMID 29312569, 2017). "Our results suggest that dietary fat intake modifies the effect of APOA5 and LEPR polymorphisms on serum triglycerides, cholesterol levels and obesity in young subjects." (PMID 26365669, 2015). "Our results suggest that dietary fat intake modifies the effect of polymorphisms at the APOA5 and LEPR genes on serum triglycerides, cholesterol levels and obesity in young subjects." (PMID 26365669, 2015). "In the development of insulin resistance and obesity, APOA5 may act as a sensor for fatty acid accumulation in adipocytes, resulting in an increased number and increased size of LDs in the liver." (PMID 38927431, 2024). "Our study aims to compare the serum levels of bone morphogenetic protein 1 (BMP1), neuregulin 4 (NRG4), and apolipoprotein A5 (ApoA5) in obese and non-obese individuals and investigate their association with obesity." (PMID 39280566, 2024). "Apoa5 promotes lipid metabolism in the development of obesity." (PMID 34502056, 2021). "Since apoA5 protein and LPL proteins interact functionally to regulate lipid metabolism, and SNPs for each gene were associated with obesity risk, so evaluating gene combinations may be more effective than single SNP analyses in identifying genetic risk." (PMID 30053818, 2018). "Since adipocytes provide the largest storage depot for TG within the lipid droplets (LDs) in humans, studies have also illuminated apoA5 could target to adipocytes and regulate intracellular TG storage, thus exerting its beneficial effect against obesity." (PMID 30053818, 2018). "The prevalence of the APOA5*2 haplotype (containing the minor allele of -1131 T > C, IVS3 + G476A and c.1259 T > C SNPs together) was 15.5% in obese children and 5.80% in the controls, and this haplotype confers susceptibility for development of obesity." (PMID 30053818, 2018). "Notably, patients with obesity or diabetes have lower plasma apoA5 levels compared with the healthy controls, and experimentally-induced hyperinsulinemia also reduced plasma APOA5 levels in healthy men." (PMID 30053818, 2018). "Therefore, our findings indicate that metformin improves obesity-related NAFLD via inhibition of hepatic apoA5 synthesis as part of the AMPK/LXRα signaling pathway." (PMID 29312569, 2017). "Here, we investigated whether metformin could improve obesity-related NAFLD through inhibition of hepatic apoA5 synthesis regulated via the AMPK/LXRα signaling pathway." (PMID 29312569, 2017).